IRS2 (insulin receptor substrate 2)
Diseases named in the same sentence as IRS2 in open-access papers (continued):
Sharing a sentence is not in itself a finding about the gene and the disease.
diabetes (continued). "In diabetes, the genes associated with lipid and glucose metabolism, such as PPARγ, IRS1 and IRS2 were genetic risk factors, and hepatic glutaminase mRNA was abundant during diabetes." (PMID 33466498, 2021). "Males Irs-2-/- mice develop diabetes at 12 weeks of age, while in females, this deletion generates obesity and a slower progression of this disease." (PMID 34220716, 2021). "Irs2 deficient mice displayed increased β-cell apoptosis and developed T2D, while upregulation of IRS2 in β-cells prevented diabetes." (PMID 32150819, 2020). "For example, β-cell specific knockout of the IR (βIRKO), global knockout of IRS1 or islet specific deletion of IRS2 (PIrs2KO) resulted in defective glucose-stimulated insulin secretion, and mice developed glucose intolerance and diabetes with age." (PMID 32150819, 2020). "Intriguingly, IRS-2-deficient mice are more susceptible to diabetes than IRS-1 knockout mice because of the impairment of insulin secretion, indicating that IRS-2 contributes to the molecular basis for diabetes." (PMID 32610588, 2020). "While IRS1 expression and phosphorylation are normal or reduced, IRS2 has normal levels in diabetes models." (PMID 32377524, 2020). "The expression of IRS-1 and IRS-2 were also increased in muscle from diabetes group when compared with control group." (PMID 33203103, 2020). "Taken together, hepatic IRS2 is downregulated in the liver in those with diabetes and fatty liver, in comparison with the liver of obese non-diabetic participants." (PMID 32710190, 2020). "Consistent with our results, it has been demonstrated that deletion of IRS1 and IRS2 genes in mice prevented activation of liver Akt-Foxo1 phosphorylation and led to the development of diabetes." (PMID 29207597, 2017). "The relationship between HIF-2α and IRS2 therefore provides a new therapeutic approach to increase IRS2 levels in the treatment of diabetes and related complications, should this be demonstrated to be therapeutically advantageous in patients." (PMID 27514532, 2016). "Hence, in the present study, we analyzed whether diabetes caused by IRS2 deficiency affects cell death in the hypothalamus, because this neuroendocrine organ is a key target for inflammation and oxidative stress in diabetes, and we analyzed the mechanisms involved." (PMID 27013528, 2016). "IRS-2 null mice displayed metabolic defects in liver, muscle, and adipose tissues and they developed diabetes owing to pancreatic β-cell failure." (PMID 24497996, 2014). "It has been previously reported that hepatic Irs1 and Irs2 play a crucial role in glucose homeostasis because simultaneous deletions of both genes in the liver (IrsLDKO) lead to diabetes in mice." (PMID 23940800, 2013). "We previously reported that FoxO1 haploinsufficiency restored β cell mass and rescued diabetes in IRS2 knockout mice." (PMID 22384192, 2012). "Deletion of IRS-2 in mice results in the development of T2DM, in part due to reduced β-cell mass, and CREB-induced IRS-2 expression prevents diabetes by promoting β-cell survival." (PMID 23049845, 2012). "Haploinsufficiency for FoxO1 resulted in an increase of β cells and rescued both IRS-2 knockout mice and Pdk-1 knockout mice from diabetes via restoration of Pdx1 expression in β cells." (PMID 22384192, 2012). "Progressive reduction in β-cell mass is responsible for the development of type 2 diabetes mellitus, and alteration in insulin receptor substrate 2 (IRS-2) abundance plays a critical role in this process." (PMID 23049845, 2012). "Homozygous replacement of WT Cdk4 with Cdk4-R24C rescued diabetes in Irs2–/– male mice." (PMID 37712417, 2023). "The upregulated expression of IRS2 can prevent the progression of diabetes." (PMID 36364802, 2022). "YQ could attenuate type 2 diabetes mellitus by improving islet α- and ß-cells via IRS-2/AKT/GLUT4 pathway and nonalcoholic fatty liver by ameliorating lipid accumulation via AMPK/PPARα/SREBP1/ACC1 pathway." (PMID 34621322, 2021).
diabetes (continued). "In addition, mRNA expression levels related to β-cell differentiation and proliferation such as NeuroD, Nkx6.1 and Irs2 were significantly higher only in combination therapy in an early phase of diabetes." (PMID 34373487, 2021). "YQ could attenuate type 2 diabetes mellitus by improving ß-cell via IRS-2/AKT/GLUT4 pathway and NAFLD by ameliorating lipid accumulation via AMPKα/ACC1/PPARα/SREBP1 pathway." (PMID 34621322, 2021). "Thus, IRS1 and IRS2 together with IGFs and IGFRs have been involved in obesity, birth weight, diabetes mellitus, insulin sensitivity and cancer, showing the genetic associations of their polymorphisms." (PMID 27483248, 2016). "Emerging gene-editing technologies, such as CRISPR (clustered regularly interspaced short palindromic repeats)/Cas9 and TALENS (transcription activator-like effector nucleases), will allow deletion or insertion of IRS1, IRS2 or both proteins in vascular cells damaged in diabetes." (PMID 27514532, 2016). "This diabetes-induced IRS2 downregulation could, by means of inhibiting the Akt-mTOR axis, contribute to the observed reduction in HIF-1α total protein level." (PMID 25381014, 2015). "The authors also suggested that change in expression of autosomal genes like insulin receptor substrate 2 (IRS2) and IGF in Turner syndrome could have an effect in modulating their increased susceptibility to type 2 Diabetes mellitus." (PMID 24932682, 2014). "Furthermore, studies have shown that β-cell-specific upregulation of IRS-2 promotes β-cell growth, survival, and insulin secretion, and therefore prevents diabetes." (PMID 23874448, 2013). "Since IRS-2 is downstream the IR for which the ligand, insulin, is markedly elevated in T2DM, our findings of higher IRS-2 in prostate cancer suggests increased risk for metastasis in men with diabetes." (PMID 23251408, 2012). "Moreover, DNA methylation of cg25924746, a CpG site located in the shore region of the IRS2 promoter-associated CpG island, was increased in the liver of individuals with type 2 diabetes, as compared with those without diabetes." (PMID 32710190, 2020). "Therefore, we speculated that improving IR and promoting IRS‐2 activation may have positive significance for diabetes‐related liver cancer." (PMID 33012117, 2020). "The ubiquitinated protein (UBD) downregulates the insulin receptor substrate protein (IRS2) in differentially expressed proteins validated by Western blot, leading to a decrease in the sensitivity of the body to insulin, which can result in the development of diabetes." (PMID 30131712, 2018). "Because some inflammatory markers are elevated in the hypothalamus of diabetic IRS2−/− mice, our aim was to analyze whether the diabetes associated with the absence of IRS2 results in hypothalamic injury and to analyze the intracellular mechanisms involved." (PMID 27013528, 2016). "Furthermore, IRS-2(−/−) mice have confirmed that insulin signalling defects in the liver, but not in skeletal muscle or adipose tissue, play a major role in the development of diabetes, particularly in combination with pancreatic β cell dysfunction." (PMID 23560040, 2013). "Finally, IRS-2, a diabetes candidate gene, has been mapped to chromosome 13 (102 cM)." (PMID 14975167, 2003). "The results revealed a contrasting pattern, with reduced NEDD8 expression in patients with type 2 diabetes mellitus, accompanied by an induction of IRS1 and IRS2 expression levels." (PMID 38272982, 2024). "In diabetes, SIRT1 enhances insulin sensitivity by deacetylating insulin receptor substrate 2 (IRS2), which boosts the insulin regulatory pathway." (PMID 38931292, 2024). "Upregulation of insulin receptor signaling is a promising approach to treat obesity and diabetes, and the action of glucose-lowering agents, such as GLP-1 and extendin-4, is usually accompanied by the increased Irs2 expression." (PMID 36297523, 2022).
diabetes (continued). "Besides, IRS-2 gene inactivation in the human will result in peripheral insulin resistance and absence of β cell expansion which may cause hyperglycaemia, diabetes and death." (PMID 34504420, 2021). "In the liver, the deletion of IRS-2 induces glucose intolerance, and in the pancreas, the deletion of IRS-2 induces diabetes." (PMID 33884100, 2021). "In this study, GC level and IRS‐2 phosphorylation in IR HCC cell models were suppressed greatly, indicating that establishing diabetes‐related liver cancer models in HCC cells by inducing IR to the cells was successful." (PMID 33012117, 2020). "Activation of stress-sensitive kinases like p38 and ERK 1⁄2 stimulates the serine phosphorylation of 1RS-1/IRS-2 which reduces insulin-stimulated IRS-1 tyrosine phosphorylation and insulin sensitivity which triggers the early onset of diabetes." (PMID 26839808, 2015). "It was demonstrated that the deletion of both IRS1 and IRS2 genes in the liver of mice (L-DKO mice) prevented activation of hepatic Akt-Foxo1 phosphorylation and resulted in the development of diabetes." (PMID 24497996, 2014). "Although to date no O-glycosylated residue is mapped on IRS-2, experimental data showed that IRS-2 also have potential to be glycosylated as IRS-1 and this glycosylation was shown to be reduced in diabetes and AD." (PMID 25580119, 2014). "A polysaccharide purified from Hovenia dulcis was found to ameliorate type 1 diabetes mellitus (T1DM) by up-regulating PDX-1, activating and up-regulating IRS2 expression, and regulating apoptosis and regeneration of islet β-cells to recover islet β-cell function injury in T1DM rats." (PMID 37894615, 2023). "The mouse models of diabetes/obesity used here did not exhibit intra-study sex differences in glucose levels, except for the IRS2 knock-out mice, where this is a known sexual dimorphism." (PMID 36891264, 2023). "Many molecules are involved in islet function and the pathogenesis of diabetes, including CD36, glucose transporters (GLUT) 2, insulin receptor substrate (IRS) 1, IRS2, pancreatic and duodenal homeobox 1 (PDX1), and peroxisome proliferator activated receptor gamma (PPARG)." (PMID 35343389, 2022). "Low levels of IR and IRS2 have been reported in islets of diabetic humans, whereas IRS2 overexpression reduces the incidence of diabetes in non-obese diabetic mice." (PMID 35327599, 2022). "Our study focuses uniquely on mechanisms leading to altered IRS2 expression in the liver of individuals with diabetes, as compared with non-diabetic participants, independent of classical risk factors, such as age, sex and obesity." (PMID 32710190, 2020). "Insulin receptor substrate 2 (IRS-2) was reported to reduce the incidence of diabetes in IRS-2-overexpressing non-obese diabetic mice." (PMID 28428639, 2017). "Indeed, our data showing that the endothelial expression of various CREB-driven angiogenic genes – including NURR1, IRS2, and more importantly, VEGF – were diminished as a function of diabetes (Dd) give credence to this proposition." (PMID 25381014, 2015). "When Irs-2 was reintroduced specifically in pancreatic β-cells using the rat insulin II promoter (RIP), Irs-2-deficient mice did not develop diabetes, as the expression of this signalling molecule restored β-cell compensation." (PMID 23560040, 2013). "Several predicted interactions were observed, many of them encompassing genes involved in the pathogenesis of diabetes, for instance miR-30e targeting IL1A and IRS2, miR-181a targeting IL1A, miR-223 targeting SLC11A2, miR-29b targeting ID1, miR-21 targeting CCL20, and many others." (PMID 24279768, 2013). "While mice globally lacking IRS-2 develop diabetes due to insulin resistance and pancreatic β cell dysfunction, NesCreIrs2KO mice do not suffer from overt and progressive diabetes due to preservation of pancreatic β-cell mass and insulin concentration." (PMID 22383997, 2012).
diabetes (continued). "From fourteen genes in the OMIM description of T2DM (Diabetes mellitus, noninsulin dependent, #125853,) five genes have a significant score in our study: Retn, Gpd2, Vegfa, Irs2 and Tcf2." (PMID 18590522, 2008). "Cdk4-R24C rescue of Irs2–/– diabetes was not due to improved insulin sensitivity." (PMID 37712417, 2023). "Thus, whole-body homozygous, but not heterozygous, replacement of Cdk4-WT with Cdk4-R24C provided effective protection against diabetes in male mice lacking IRS2." (PMID 37712417, 2023). "It is found that mice lacking IRS-2 have a better chance to develop diabetes." (PMID 34504420, 2021). "Thus, we speculated that SHP2 may stimulate the occurrence of diabetes‐related liver cancer, whereas SHP2 silencing could inhibit IRS‐2 phosphorylation by regulating the activation of AKT and ERK1/2, thus ameliorating glucose uptake and IR." (PMID 33012117, 2020). "Mice lacking IRS-2 develop diabetes due to reduced β cell mass and peripheral insulin resistance." (PMID 22384192, 2012). "If the efficacy of insulin signaling does indeed play an important role in DRG function, it is reasonable to propose that factors common to both diabetes models could play an important role in modulating IRS2 signaling regardless of available insulin levels." (PMID 21754917, 2011). "We identify retarded renal growth in male and female Irs2-/- mice, independent of diabetes." (PMID 20604929, 2010). "We further investigated the clinical relevance by analyzing the expressions of Insulin, IRS1, IRS2, and NEDD8 in ovarian cancer tissues from patients with or without type 2 diabetes mellitus." (PMID 38272982, 2024). "Notably, in the context of high-grade serous carcinoma (HGSC) patients, whether they had type 2 diabetes mellitus or not, IRS1 and IRS2 displayed a parallel relationship with each other while exhibiting an inverse relationship with NEDD8." (PMID 38272982, 2024).
Obesity (70 papers, 2008 to 2026). Accumulation of substantial excess body fat. "An obesity-associated increase in serum TC and TG levels aggravates liver injury, increases gluconeogenesis, accelerates glycogen breakdown, and blocks the IRS2/PI3K/AKT signaling pathway." (PMID 39458511, 2024). "Recently, it was shown that the obesity-associated decreased expression of insulin receptor substrate-2 (Irs2) in macrophages attenuated the M2 macrophage activation by IL-4." (PMID 37571282, 2023). "Congenital and acquired factors (e.g., genetic defects, gene mutations, obesity, and the environment) affect the IRS2/PI3K/AKT/GSK3β/GLUT4 pathway, causing IR." (PMID 32273844, 2020). "Although not significant, there was a trend of reduced AKT2 mRNA expression in 4-week-old offspring (P = 0.056), and reduced IRS2 mRNA expression in 12-week-old offspring (P = 0.052), which was associated with maternal obesity exposure during lactation." (PMID 31300679, 2019). "The translational value of this receptor is further enhanced with data that shows a positive association between the A2bAR and BMI, parameters of obesity (e.g. waist and hip circumference) and IRS-2 in subcutaneous fat samples obtained from obese patients." (PMID 22848385, 2012). "Both of them are important for insulin signaling within the brain: Genetic variation within the IRS-1 locus was shown to determine insulin responsiveness of the human brain and partially dysregulated IRS-2 signaling causes hyperphagia and obesity in animals." (PMID 21738722, 2011). "Lautier and coworkers suggested that IRS2 haplotypes were associated with severe obesity (BMI ≥40 kg/m2) among French individuals, but a later report by Sweeney and colleagues did not confirm this association among US white and Hispanic women." (PMID 18611262, 2008). "Myeloid Irs2 deficiency results in enhanced FoxO1 activity in macrophages, which impairs IL-4–induced M2 macrophage activation and predisposes to developing dietary obesity and hyperinsulinemia in mice." (PMID 35700043, 2022). "We believe that the IRS2 (Gly1057Asp) polymorphism influence glucose homeostasis and obesity." (PMID 34449768, 2021). "Consistent also with the obesity linkage to Irs2 mutations, the mice exhibited some weight gain." (PMID 33330474, 2020). "Receiver operating characteristic curves manifested that the efficacy of NCAPH and IRS2 in distinguishing between disease (obesity/NAFLD) and normal samples was all excellent." (PMID 42137875, 2026). "Subsequently, based on the results of LASSO and SVM-RFE, we gained two shared biomarkers (NCAPH and IRS2) in obesity and NAFLD, and IRS2 was down-regulated and NCAPH was up-regulated in disease (obesity/NAFLD) samples." (PMID 42137875, 2026). "Conclusively, HB alleviates HFD-induced obesity and liver injury in a rat model of obesity possibly via the IRS2/PI3K/Akt signaling pathway." (PMID 39458511, 2024). "In line with this study, mice with macrophage insulin receptor substrate 2 (IRS2) deletion demonstrated protection from HFD-induced obesity and glucose intolerance due to increased energy expenditure via enhanced BAT activity and WAT beiging." (PMID 37153549, 2023). "In obesity, IR is demonstrated by the downregulation of IRS2 and persistent expression of IRS1, and inflammatory cytokines including TNF-α downregulate IRS2 mRNA expression." (PMID 34135978, 2021). "Importantly, our cohort showed negligible impact of confounding factors such as age, sex and BMI on IRS2 gene expression, as proven by linear regression models supporting our hypothesis that aberrant IRS2 expression might cause a diabetic phenotype independently of obesity." (PMID 32710190, 2020). "This study revealed pleiotropic protective effects of DPP-4 inhibitor SIT on cardiac function, glycemia, and β-cell function together with reducing S6K1 activation and IRS-1 and IRS-2 degradation in the obesity female mouse model." (PMID 30116740, 2018).